GDF15 (growth differentiation factor 15)
Diseases named in the same sentence as GDF15 in open-access papers (continued):
Sharing a sentence is not in itself a finding about the gene and the disease.
gastric cancer (continued). "Furthermore, serum GDF15 levels were remarkably higher in the gastric cancer group than in the normal gastric group." (PMID 36769245, 2023). "In summary, our findings show that GDF15 functions in tumorigenesis in gastric cancer patients." (PMID 36769245, 2023). "In addition, our study demonstrated that GDF15 is involved in cell proliferation, migration, and invasion in gastric cancer via STAT3/MYC signaling." (PMID 36769245, 2023). "We further analyzed serum GDF15 levels in normal gastric and gastric cancer patients." (PMID 36769245, 2023). "From our results, we speculated that GDF15 might be related to the migration and invasion of gastric cancer cells." (PMID 36769245, 2023). "Furthermore, multivariate analysis showed that age (p = 0.001), stage (p = 0.001), and GDF15 expression (p = 0.048) were prognostic factors for survival in gastric cancer patients." (PMID 36769245, 2023). "We next investigated the mechanisms by which GDF15 induces carcinogenesis in gastric cancer cells." (PMID 36769245, 2023). "We thus examined whether the blockade of GDF15 affected the STAT3 activation in gastric cancer cells." (PMID 36769245, 2023). "Additionally, GDF15 knockdown in gastric cancer cells considerably reduced cell proliferation by inducing G0/G1 cell cycle arrest." (PMID 36769245, 2023). "Nevertheless, the role of GDF15 signaling in gastric cancer is unclear." (PMID 36769245, 2023). "Nevertheless, the functional mechanism of GDF15 in gastric cancer is still unclear." (PMID 36769245, 2023). "The present study demonstrated that GDF15-mediated STAT3 activation induced EMT in gastric cancer." (PMID 36769245, 2023). "GDF15 was an independent predictor of reduced overall survival in patients with gastric cancer." (PMID 36769245, 2023). "Furthermore, to determine the association between GDF15 and STAT3 in gastric cancer, we analyzed their correlation in the GEPIA dataset." (PMID 36769245, 2023). "The GDF15 expression changes have also been detected in many tumors, including gastric cancer." (PMID 34149933, 2021). "The function of GDF15 in the pathogenesis and progression of gastric cancer remains unclear since the experimental data support both the antitumorigenic or pro-tumorigenic activity of this multifunctional cytokine." (PMID 34149933, 2021). "Others, again, observed induction of apoptosis by GDF-15 in gastric cancer cells." (PMID 32508832, 2020). "It has been shown that ErbB2 is transactivated by GDF15 in human breast and gastric cancer cells." (PMID 29636108, 2018). "Similarly, a study done among a cohort of gastric cancer patients did not demonstrate any association between blood transfusion and circulating GDF15 levels." (PMID 36806122, 2023). "Consequently, our study suggests that the GDF15/STAT3 signaling axis may be an effective prognostic target for patients with gastric cancer." (PMID 36769245, 2023). "Consequently, it is necessary to understand the molecular mechanism of GDF15 in gastric cancer." (PMID 36769245, 2023). "Here, we report that the high expression of GDF15 was associated with invasion depth (p = 0.002), nodal involvement (p = 0.003), stage III/IV (p = 0.01), lymphatic invasion (p = 0.05), and tumor size (p = 0.049), which are related to poor survival in gastric cancer patients." (PMID 36769245, 2023). "However, GDF15 is up-regulated in some malignant tumors, such as gastric cancer in humans." (PMID 34434660, 2021). "In gastric cancer, increased levels of GDF-15 were associated with reduced progression-free and overall survival in univariate analyses; in multivariate analyses, high GDF-15 in combination with MMP7 and miR-200c was an independent predictor for death (p = 0.033)." (PMID 32508832, 2020). "The biological role and action mechanism of GDF15 were investigated by examining the effect of GDF15 knockdown in AGS and SNU216 gastric cancer cells." (PMID 36769245, 2023).
gastric cancer (continued). "The knowledge about the role of GDF15 and its signaling through a GFRAL/RET-dependent complex in gastric cancer is only beginning to be recognized, similar as in other human cancers." (PMID 34149933, 2021). "In addition, TIMER2.0 data analysis showed that high expression of GDF15 or EGR4+GDF15+ and increased CAFs infiltration in gastric cancer patients had a significantly shorter survival time." (PMID 41203604, 2025). "It has been shown that ROS builds up in the gastric carcinoma cells after exposure to 5-FU activates HIF-1α-(HMGB1) signaling, which recruits M2 TAMs, which generates GDF15 (growth differentiation factor 15), and enhances fatty acid β-oxidation thus increasing the chemoresistance in them." (PMID 38347575, 2024). "Moreover, GDF15 promotes cancer progression via the phosphorylation of STAT3 and cell-cycle-related proteins in gastric cancer." (PMID 36769245, 2023). "Here we tested correlation between serum GDF15 and CRP levels in our samples from gastritis patients and also tested correlation between serum GDF15 levels and histological differentiation grade in our samples from gastric cancer patients." (PMID 26892343, 2016). "Exposure of LNT-229 or LN-308 cells to recombinant GDF-15 did not trigger Smad2 or Smad1/5/8 phosphorylation, a finding that is in line with previous reports in gastric cancer cells." (PMID 26741507, 2016). "However, the mechanism by which GDF15 contributes to the tumor progression of gastric cancer is not well defined." (PMID 36769245, 2023). "When we further screened whether these signaling pathways are perturbed in GDF15-knockdowned gastric cancer cells, we found that the activation of AKT, ERK, p38, and NF-κB was not different between shCtrl and GDF15-knockdown gastric cancer cells." (PMID 36769245, 2023). "Moreover, we examined ten pairs of gastric cancer tissues and adjacent non-malignant gastric tissues for GDF15 protein levels using Western blotting analysis." (PMID 36769245, 2023). "Moreover, GDF15 could induce apoptosis by upregulating death receptor-4 (DR4) and DR-5 expression in gastric cancer cells." (PMID 29262584, 2017). "Transcriptomic profiling of paired neoplastic and non-neoplastic gastric mucosa from 61 gastric cancer patients revealed a significant upregulation of both LIF and GDF15 in tumor tissue, with a strong positive correlation between their expression levels." (PMID 41744798, 2026).
Hepatic steatosis (34 papers, 2016 to 2026). Steatosis is a term used to denote lipid accumulation within hepatocytes. "The study also found a significant association between serum GDF15 levels and hepatic steatosis and fibrosis, measured by the fatty liver index and the Fib-4 index." (PMID 40650260, 2025). "Recent studies have underscored the crucial function of GDF-15 in glucose and lipid metabolism, with growing interest in its association with fatty liver disease." (PMID 41333917, 2025). "GDF15 has emerged as a notable biomarker in metabolic dysfunction-associated fatty liver disease/metabolic dysfunction-associated steatohepatitis (MASLD/MASH) through cross-species investigations." (PMID 40837873, 2025). "Although the underlying mechanism whereby GDF15 protects against hepatic steatosis is unclear, our data suggest that GDF15 and FGF21 have differing roles in liver fat homeostasis." (PMID 33718833, 2021). "We evaluated the metabolic phenotypes of LKO mice with global deficiency of GDF15 or FGF21 and show that GDF15 regulates body and fat mass and prevents diet-induced hepatic steatosis, whereas FGF21 upregulates insulin sensitivity, energy expenditure, and thermogenesis in white adipose tissue." (PMID 33718833, 2021). "Elevated GDF15 levels have been observed in the liver of obese mice and humans with hepatic steatosis." (PMID 40837873, 2025). "In diet-induced MASH mice, GDF15 ablation exacerbates hepatic steatosis, inflammation, fibrosis, and liver injury, while transgenic GDF15 expression alleviates these phenotypes and metabolic deterioration." (PMID 40243151, 2025). "While GDF15 regulates body fat mass and reverses hepatic steatosis, FGF21 increases insulin sensitivity and thermogenesis due to hepatic mitochondrial dysfunction." (PMID 37538245, 2023). "Since GDF15 levels predict fatty liver disease and energy balance disorders, further studies are warranted to determine the effect of GDF15 in mediating the metabolic disturbances that occur in mouse models and PLWH." (PMID 35510313, 2022). "Since GDF15 levels predict fatty liver disease and energy balance disorders, further studies are warranted to determine the effect of GDF15 in mediating the metabolic disturbances that occur in Vpr mice and PLWH." (PMID 35510313, 2022). "Clearly, further investigations using e.g., transient elastography should clarify a link between GDF15 and progression of fatty liver disease in our study cohort." (PMID 33003626, 2020). "Consistently, recombinant GDF15 treatment significantly reduces hepatic steatosis in mice." (PMID 40243151, 2025). "In animal models, both recombinant GDF15 and its overexpression have been shown to reduce hepatic steatosis, inflammation, and fibrosis, independent of weight loss." (PMID 40837873, 2025). "During metabolic liver disease progression, particularly at the critical transition stage from metabolic dysfunction-associated fatty liver disease (MASLD) to MASH, hepatic stress signaling activates transcription factors TFEB and DDIT3 to cooperatively regulate Gdf15 transcription." (PMID 40837873, 2025). "In addition to changes in food intake and body weight, recombinant GDF15 also reduces liver steatosis and improves glycemic control via GFRAL in genetically induced and DIO mouse models." (PMID 37818094, 2023). "Despite the very modest impact of GDF15 and FGF21 ‘loss-of-function’ on body weight, they remain of considerable interest as pharmacological ‘gain-of-function’ targets in relation to their impact on body weight and on hepatic steatosis." (PMID 36064109, 2022). "It is likely that the upregulation of GDF15 might be a protective mechanism against the inflammatory response induced by free fatty acids in the context of fatty liver disease and the inflammation sustained by macrophages that leads to NASH and fibrosis." (PMID 35194014, 2022). "Moreover, hepatic steatosis and liver triglyceride content were elevated in 20‐month‐old Gdf15 KO mice." (PMID 32691494, 2020).
Hepatic steatosis (continued). "Importantly, we found that Gdf15 deletion exacerbated hepatic steatosis, inflammation and fibrosis in NASH animal models using MCD or AMLN diet." (PMID 29717162, 2018). "In addition, studies on mice with NAFLD have shown that GDF-15 may ameliorate hepatic steatosis and NASH through direct anti-steatotic and anti-inflammatory effects that may be independent of reduction in body weight." (PMID 40794228, 2025). "Furthermore, additional studies demonstrated that GDF15 expression in the liver can significantly promote beta-oxidation of fatty acids and ketogenesis in hepatocytes, thus playing a protective role against hepatic steatosis and inflammation." (PMID 35194014, 2022). "Nowadays, it is emerging that GDF15 significantly influences the development and progression of MASLD by improving insulin resistance and attenuating hepatic steatosis, inflammation, and fibrosis." (PMID 40650260, 2025). "In conclusion, our results indicate that GDF15 is induced in NASH livers in a manner dependent on ER stress, which serves as a protective mechanism to attenuate hepatic steatosis, inflammation, fibrosis and metabolic deterioration." (PMID 29717162, 2018). "In the present study, we showed that Gdf15 deletion led to aggravated hepatic steatosis, inflammation and fibrosis in mice after NASH diet, while mice overexpressing GDF15 exhibited improvement of these phenotypes." (PMID 29717162, 2018). "Notably, circulating GDF-15 has been reported to be higher in advanced fibrosis, lower in NASH and even lower in hepatic steatosis, thus being suggested as a promising predictor of hepatic fibrosis in human NAFLD." (PMID 40794228, 2025). "Overexpression of farnesoid X receptor (FXR), (NSAID)‐activated gene‐1 (NAG‐1), and growth differentiation factor‐15 (GDF15) ameliorates liver steatosis, reduces lipogenesis, and enhances lipolysis and fatty acid β‐oxidation, while concurrently suppressing AIM2 inflammasome activation." (PMID 39158380, 2025). "Notably, GDF15 partially mediates the resistance to DIO, but is necessary for the improvement in glucose homeostasis and hepatic steatosis following high-fat feeding in OPA1 BKO mice." (PMID 37819027, 2023). "Furthermore, we also unveiled a role for GDF15 in attenuating DIO and improving glucose clearance and hepatic steatosis in OPA1 BKO mice." (PMID 37819027, 2023). "Moreover, GDF15 neutralization abrogated the beneficial effects of CPT on glucose homeostasis and prevention of hepatic steatosis." (PMID 35202387, 2022). "We also showed aggravated hepatic steatosis, inflammation, fibrosis and metabolic deterioration in Gdf15-knockout (Gdf15−/−) mice fed two different NASH diets, while these pathologic and metabolic features were attenuated in GDF15-transgenic (GDF15-Tg) mice." (PMID 29717162, 2018). "Growth Differentiation Factor 15 (GDF-15), a stress-induced cytokine, has been suggested to protect against fibrosis progression through neuro-metabolic-immunologic pathways and to regulate energy and lipid homeostasis, potentially influencing hepatic steatosis." (PMID 41836939, 2026). "Similarly, the mammalian mitokine GDF15 has been studied extensively for: (i) its expression regulated by the ISR, (ii) its metabolic regulation through suppression of food intake and controlling energy intake and (iii) its ability to prevent diet-induced hepatic steatosis." (PMID 37538245, 2023). "Similar to GDF15, FGF21 reduces the body weight through a non-adipose tissue effect; increases insulin sensitivity, adaptive thermogenesis, and uncoupling protein 1 (UCP1)-independent EE; and reverses hepatic steatosis." (PMID 33718833, 2021).
pulmonary hypertension (34 papers, 2011 to 2026). Increased pressure within the pulmonary circulation due to lung or heart disorder. "GDF15 is also associated with left ventricular dysfunction as induced by pulmonary hypertension, especially in the case of persistent heart disease." (PMID 37093513, 2024). "An elevated systemic GDF15 level is associated with the risk, progression, and severity of pulmonary hypertension by increasing atrial and pulmonary capillary wedge pressure, which are caused by hypoxia and laminar shear stress in pulmonary vascular endothelial cells." (PMID 37093513, 2024). "In a study of children with congenital heart disease complicated by pulmonary hypertension, the GDF15 serum level was found to be considerably increased, which was positively associated with the level of N-terminal pro-brain natriuretic peptide (NT-proBNP)." (PMID 37093513, 2024). "According to existing studies, the expression level of GDF-15 in pulmonary hypertension is indeed increased, and it is correlated with the survival rate of patients." (PMID 37288264, 2023). "Patients with pulmonary arterial hypertension with elevated GDF-15 levels have higher pulmonary arterial pressure, higher pulmonary vascular resistance, and more serious pulmonary vascular lesions, which are potentially more harmful." (PMID 37288264, 2023). "As per a study, GDF-15 in systemic sclerosis patients with pulmonary arterial hypertension increased significantly and the survival rate decreased compared to those without pulmonary arterial hypertension." (PMID 37288264, 2023). "Noteworthily, there are also several other biomarkers including circulating angiogenic modulatory factors (VEGFR1, CRP, endostatin, or PCEB-ACE) or inflammatory markers (galectin-3, GDF-15) which were related to the pathophysiology of pulmonary hypertension." (PMID 32566097, 2020). "GDF15 levels have been reported to be as a useful biomarker in chronic obstructive pulmonary disease, lung fibrosis and pulmonary arterial hypertension and predict disease severity, decline in lung function and mortality." (PMID 33344478, 2020). "The aim of the study was to examine the expression and biological roles of GDF-15 in the lung of patients with pulmonary arterial hypertension (PAH)." (PMID 21548946, 2011). "A team of authors from the University of Colorado demonstrated significantly elevated plasma levels of GDF-15 in patients with systemic sclerosis-associated pulmonary arterial hypertension (SSc-PAH) compared to SSc patients without PAH." (PMID 38668313, 2024). "Their study confirmed that GDF-15 increased in 76% of patients with pulmonary hypertension, and found that the increased GDF-15 level was related to older age, higher NYHA level, shorter 6 min walking distance, higher average right atrial pressure, and higher NT-proBNP." (PMID 37288264, 2023). "Therefore, in future research, it is necessary to increase the sample size for further study on prognosis correlation, and further research is needed to confirm the predictive ability of GDF-15 and prognosis of patients with pulmonary arterial hypertension." (PMID 37288264, 2023). "Previous studies also suggested that increased expression of GDF-15 may mediate muscle atrophy in pulmonary arterial hypertension and intensive care unit-acquired weakness patients." (PMID 35379793, 2022). "Furthermore, it has been shown that GDF-15 serum levels are increased in scleroderma patients with pulmonary hypertension and GDF-15 protein was predominantly located in monocytes infiltrating the lung tissue." (PMID 21548946, 2011). "In addition, normal GDF-15 ruled out the risk of death or transplantation within 2 years after diagnosis of pulmonary arterial hypertension." (PMID 37288264, 2023). "GDF-15 might induce muscle atrophy via suppressing TAK1 in pulmonary arterial hypertension (PAH)." (PMID 35379793, 2022).
pulmonary hypertension (continued). "Neither CAC nor GDF-15 correlated with pulmonary artery enlargement, as determined by the ratio of pulmonary artery and aorta diameters (PA:A ratio), implying that this association did not reflect occult pulmonary hypertension." (PMID 28245821, 2017). "GDF15 expression is increased in the lung of patients with pulmonary arterial hypertension and predominantly locates in pulmonary microvascular endothelial cells, while whether GDF15 can be induced in endothelial cells under hyperglycemic conditions is unknown." (PMID 23799024, 2013). "In pulmonary arterial hypertension (PAH), oxygen delivery negatively correlates with GDF15 levels in patients with R‐L shunts." (PMID 40019842, 2025). "Independence from the anorexigenic effects of GDF‐15 are supported by its association with muscle size and function, but not BMI in COPD and pulmonary arterial hypertension." (PMID 40842041, 2025). "Serum GDF15 levels were elevated in patients with pulmonary hypertension (PH) and SSc compared with patients with SSc but not PH, as well as in patients with SSc, ILD and more pronounced skin lesions." (PMID 39156689, 2024).